SOD2 (superoxide dismutase 2)
Diseases named in the same sentence as SOD2 in open-access papers (continued):
Sharing a sentence is not in itself a finding about the gene and the disease.
varicocele (2 papers, 2015 to 2022). A condition characterized by the dilated tortuous veins of the spermatic cord with a marked left-sided predominance. "Some of the DEP in unilateral varicocele group including PRDX1, SOD1, SOD2 were shown to be involved in the removal of superoxide." (PMID 25890347, 2015).
vasculitis (2 papers, 2021 to 2024). "However, the associations of hsa-miR-6780, SOD2, and LINC00999 with vasculitis and KD have not been reported till now." (PMID 34026343, 2021).
ventricular dilation (2 papers, 2018 to 2025). "Moreover, deficiency of SOD2, a mitochondrial antioxidant enzyme that converts superoxide to hydroperoxide, has been shown to result in enlarged hearts and left ventricular dilation in mice." (PMID 30116150, 2018).
acute liver failure (1 paper, 2022). Rapid deterioration of liver function causing encephalopathy and coagulopathy. "SOD staining in liver tissues revealed an increased expression of SOD2, also known as manganese-dependent SOD (MnSOD), in patients with acute liver failure (ALF), and the plasma SOD level was increased and associated with disease severity." (PMID 35123412, 2022).
acute lymphoblastic leukaemia (1 paper, 2023). "One study on acute lymphoblastic leukaemia reported an association between the SOD2 gene variant rs4880 and hepatotoxicity in patients undergoing asparaginase-based therapy." (PMID 37469404, 2023).
adrenal cancers (1 paper, 2021). A carcinoma involving a adrenal gland. "Reduced expression of SOD2 was correlated with poorer survival of patients with aggressive thyroid or adrenal cancers." (PMID 34200699, 2021).
aging (1 paper, 2024). A developmental process that is a deterioration and loss of function over time. "Reduced SOD2 activity and mitochondrial oxidative stress have been shown to be associated with skin and brain aging." (PMID 38384969, 2024).
alcohol (1 paper, 2021). "The gene expression changes of superoxide dismutase 2 (SOD2) and glutathione peroxidase 1 (Gpx1) related to acute alcohol liver injury were investigated at 3 h after alcohol injection." (PMID 34959956, 2021).
alcohol addiction (1 paper, 2023). "Although rs4880 is the most studied genetic variant of SOD2, this is the first time that an association between obsessive–compulsive symptoms and alcohol addiction has been revealed." (PMID 38275640, 2023). "However, to our knowledge, there are no studies that focus on the genetic variability of PON1, SOD2, GPX1, IL1B, IL6, interleukin 6 receptor (IL6R), and miR146a related to the risk of alcohol addiction, and patients’ comorbid psychosymptomatology." (PMID 38275640, 2023). "Thus, we focused on the role of PON1 rs705379, rs705381, rs854560, and rs662, SOD2 rs4880, GPX1 rs1050450, IL1B rs1143623, rs16944, and rs1071676, IL6 rs1800795, IL6R rs2228145, and miR146a rs2910164 in alcohol addiction, and patients’ comorbid psychosymptomatology." (PMID 38275640, 2023).
anaplastic thyroid carcinoma (1 paper, 2020). "A microarray expression analysis of the Oncomine database demonstrated that SOD2 is higher expressed in PTCs and pronounced higher expressed in anaplastic thyroid carcinoma in comparison to normal thyroid tissue." (PMID 32603365, 2020).
aneurysm (1 paper, 2025). Bulging or ballooning in an area of an artery secondary to arterial wall weakening. "Our findings that augmented expression of SOD2 mitigated aneurysm progression and rupture in experimental AAA elucidated the pivotal role of this antioxidant enzyme and revealed additional regulatory pathways downstream of its activities." (PMID 40213658, 2025). "We hypothesize that augmented expression of SOD2 will protect against oxidative stress and mitigate aneurysm progression." (PMID 40213658, 2025). "Given the observed relative deficiency of SOD2 in established AAA, we hypothesized that augmentation of SOD2 expression in aortic tissue would mitigate aneurysm progression." (PMID 40213658, 2025).
Becker muscular dystrophies (1 paper, 2015). "A significant reduction in SOD2 expression was also noted in Duchenne and Becker muscular dystrophies." (PMID 25880557, 2015).
benign thyroid tumors (1 paper, 2022). "Thus, SOD2 overexpression in mice with benign thyroid tumors resulted in an increased tumor burden." (PMID 36552527, 2022).
bone marrow failure (1 paper, 2017). "It was reported that IR-induced ROS stress contributes to IR-induced bone marrow failure in hematopoietic cells partly via downregulating the activity of SOD2." (PMID 28814292, 2017).
Brain atrophy (1 paper, 2016). Partial or complete wasting (loss) of brain tissue that was once present. "In addition, oral herbal formula B401 treatment effectively alleviates brain atrophy and enhances brain BDNF expression, improves subcutaneous blood flow and enhances brain VEGF expression, and reduces blood ROS and enhances brain SOD2 expression but reduces brain 3-NT expression in 3× Tg-AD mice." (PMID 27761145, 2016).
Cachexia (1 paper, 2017). Severe weight loss, wasting of muscle, loss of appetite, and general debility related to a chronic disease. "In the current study, levels of cytosolic SOD1, but not those of SOD2, were significantly greater in the limb muscle of the cancer-cachexia rats than in control animals." (PMID 29255650, 2017). "SOD2 protein levels did not significantly differ between cancer-cachexia and the non-cachexia control rats." (PMID 29255650, 2017). "In cancer-cachexia rats, treatment with formoterol did not significantly modify protein SOD1, SOD2, or catalase levels in either diaphragm or gastrocnemius muscles." (PMID 29255650, 2017).
carotid atherosclerosis (1 paper, 2008). A thickening and loss of elasticity of the walls of carotid arteries that occur with formation of atherosclerotic plaques. "SNP in the signal sequence of SOD2 (Ala16Val) appears to be a minor determinant of carotid atherosclerosis." (PMID 18423055, 2008).
cervical disease (1 paper, 2021). "However, the results presented in our study clearly indicate that the levels of expression of this protein are associated with DFS and OS in patients with stage IIIB squamous cell carcinoma of the cervix, suggesting that SOD2 expression may be considered a biomarker for cervical disease outcome." (PMID 34062984, 2021).
childhood asthma (1 paper, 2017). "The SOD2 gene variant was also found to be associated with childhood asthma." (PMID 28208751, 2017).
Cirrhosis (1 paper, 2021). A chronic disorder of the liver in which liver tissue becomes scarred and is partially replaced by regenerative nodules and fibrotic tissue resulting in loss of liver function. "All the patients with cirrhosis had at least one risk allele for SOD2 rs4880 SNP too." (PMID 34746177, 2021).
clear cell carcinoma (1 paper, 2019). "In both endometrioid and clear cell carcinomas, SOD2 positivity was seen as strong dot-like structures in the cytoplasm, suggesting mitochondrial expression." (PMID 30700285, 2019). "SOD2 expression was not affected by patients’ age, high FIGO tumor stage (stage 1–2 vs 3–4), presence of significant blood markers (yes vs no), histology (clear cell carcinoma vs endometrioid carcinoma), and optimality of adjuvant primary treatment (yes vs no)." (PMID 30700285, 2019).
Crohn disease (1 paper, 2017). A gastrointestinal disorder characterized by chronic inflammation involving all layers of the intestinal wall, noncaseating granulomas affecting the intestinal wall and regional lymph nodes, and transmural fibrosis. "Association of SNPs in the antioxidant system genes SOD2 and GPX1 with Crohn’s disease clinical characteristics." (PMID 28052094, 2017). "Moreover, we found nominal significant associations between SOD2 and Crohn’s disease susceptibility and disease subphenotypes but these did not withstand the correction for multiple testing." (PMID 28052094, 2017).
Cryptococcal meningitis (1 paper, 2021). Meningeal inflammation produced by cryptococcus neoformans, an encapsulated yeast that tends to infect individuals with acquired immunodeficiency syndrome and other immunocompromised states. "Replacement of Sod1 with cytosolic Sod2 is required to maintain cellular superoxide buffering and contributes to the ability of C. neoformans to resist oxidative stress and impacts colonization of the brain during cryptococcal meningitis." (PMID 33567338, 2021).
cryptorchid (1 paper, 2019). "Here, we showed that SOD2 protein expression in canine cryptorchid condition was significantly reduced compared to NT." (PMID 31824429, 2019).
deafness (1 paper, 2025). An inherited or acquired condition characterized by the complete loss of the ability to hear from one or both ears. "Thus, our study explores the role of the deafness gene PRPS1 in HL, particularly through the NAD+/SIRT3/SOD2 pathway." (PMID 40677922, 2025).
dialysis (1 paper, 2021). "We found a higher expression of SOD2 in patient PBMCs, which is in agreement with earlier studies reporting higher SOD2 gene expression in hemodialysis and peritoneal dialysis patients compared to healthy controls." (PMID 33790861, 2021).
E. coli infection (1 paper, 2022). "E. coli infection destroyed the antioxidant capacity of bMECs by reducing the expression of antioxidant enzyme-encoding genes (Nrf2 and SOD2)." (PMID 36341408, 2022). "Additionally, the protein expression of Nrf2 and SOD2 was consistent with the gene expression compared to the results of the reversed downregulation of Nrf2 and SOD2 induced by E. coli infection." (PMID 36341408, 2022).
emphysema (1 paper, 2017). "This is corroborated by our findings that mitochondrial antioxidant SOD2 and histone deacetylase SIRT3 were reduced in mouse lungs with emphysema." (PMID 28186975, 2017). "Therefore, the alterations of p66shc, SOD2 and SIRT3 may link mitochondrial ROS, biogenesis and dynamics to cellular senescence during the development of COPD/emphysema." (PMID 28186975, 2017).
erysipelas (1 paper, 2017). An infection of the upper layers of the skin caused by species of streptococcus. "Our data provides evidence suggesting this SOD2 substitution of leucine to phenylalanine increases susceptibility to erysipelas and was linked to the more severe bullous form of the infection." (PMID 28512644, 2017). "Our results show that increased serum IL1-β level in erysipelas patients is the T allele of SOD2 SNP C2734T dependent." (PMID 28512644, 2017). "Our observation linked the high levels of expressed CCL5 in erysipelas patients who were linked to the homozygous T genotype in SOD2 C2734T SNP." (PMID 28512644, 2017). "An association was found between SOD2 C2734T SNP and the risk of erysipelas." (PMID 28512644, 2017). "Comparing 71 erysipelas patients to 55 age-matched healthy individuals, we sought for CAT, SOD1, and SOD2 single polymorphism mutation (SNPs) interactions with erysipelas' predisposition and serum cytokine levels in the acute and recovery phases of erysipelas infection." (PMID 28512644, 2017). "Therefore, we conclude that the SNP SOD2 C60T has a limited effect on the predisposition to erysipelas." (PMID 28512644, 2017). "The presence of SOD1 G7958, SOD2 T2734, and CAT C262 alleles was linked to erysipelas' predisposition." (PMID 28512644, 2017). "Currently, our knowledge on the association between SOD1, SOD2, and CAT gene expression and severity of erysipelas is limited." (PMID 28512644, 2017). "Our data demonstrated lack of association between the SOD2 C60T SNP and predisposition to erysipelas." (PMID 28512644, 2017). "The frequency of the SOD2 C60T SNP allele and genotype distribution in the erysipelas patients and controls were not significantly different." (PMID 28512644, 2017). "Interestingly, we have found increased serum level of HGF in erysipelas with C/C genotype of SOD2 C2734T." (PMID 28512644, 2017). "There was a lack of predisposition to erysipelas in SOD2 T/T genotype (OR = 2.3, 95% CI = 0.93–5.72, p < 0.0724) when compared to the C/T and C/C genotypes combined." (PMID 28512644, 2017). "However, when SNPs were analyzed based on the form of erysipelas, a significant difference (p < 0.001) in frequency of SOD2 (T2734C) was found between the bullous and erythematous forms of erysipelas." (PMID 28512644, 2017). "Also, correlation between expression of SOD1, SOD2, and catalase genes and activation of inflammatory cytokine in erysipelas still remain unknown." (PMID 28512644, 2017). "Therefore, we sought to determine whether single-nucleotide polymorphisms (SNPs) in the genes encoding SOD1, SOD2, CAT, and cytokine levels and their interaction can serve as susceptibility markers for erysipelas." (PMID 28512644, 2017). "Therefore, we suggest that SOD2 C60T SNP has limited role in pathogenesis of erysipelas." (PMID 28512644, 2017). "There were lack of differences in the distribution of SOD1 (G7958A), SOD2 (T2734C), SOD2 (C60T), and CAT (C262T) SNPs in subjects with erysipelas based on gender, multiplicity, and severity of the disease (p > 0.05)." (PMID 28512644, 2017).
erythroleukemia (1 paper, 2020). Acute erythroid leukemia characterised by the presence of at least 50% erythroid precursors and at least 20% myeloblasts in the bone marrow. "To test this hypothesis, we genetically disrupted the SOD2 gene using the CRISPR/Cas9 genetic strategy in a human erythroleukemia cell line (HEL 92.1.7) capable of induced differentiation toward an erythroid phenotype." (PMID 33585836, 2020).
esophageal adenocarcinoma (1 paper, 2019). A malignant tumor with glandular differentiation arising predominantly from Barrett mucosa in the lower third of the esophagus. "NADPH oxidase NOX5-S-derived ROS then promote cell proliferation and survival, whereas SOD2, stimulated by NFκB and ZEB2, is involved in EMT of esophageal adenocarcinoma cells." (PMID 29478325, 2019).
esophageal squamous cell carcinoma (1 paper, 2020). Esophageal squamous cell carcinoma (ESCC) is a type of esophageal carcinoma (EC) that can affect any part of the esophagus, but is usually located in the upper or middle third. "Indeed, a study in esophageal squamous cell carcinoma suggested that an increase in the SOD-2 levels resulted in resistance to cisplatin in the related cells." (PMID 33086722, 2020).
esophageal tumor (1 paper, 2021). "The SOD2 expression was also increased in samples of esophageal tumor tissue, compared to tissues without neoplasia." (PMID 34062984, 2021).
fluorosis (1 paper, 2023). "In addition, among bone health problems caused by some special factors, such as fluorosis and manganese superoxide dismutase (SOD2) deficiency, aerobic exercise has also been confirmed to play a therapeutic role and to protect bone from oxidative stress damage." (PMID 37196112, 2023).
galactosemia (1 paper, 2014). "A recent experiment using STZ-induced diabetic rats and experimentally induced galactosemia models showed that glycemia memory induces histone modification at the retinal manganese superoxide dismutase gene (SOD2)." (PMID 25180070, 2014).
gout (1 paper, 2019). A condition characterized by painful swelling of the joints, which is caused by deposition of urate crystals. "There was increased expression of TXNRD1 in the monocytes from gout patients, but no change in expression of SOD2 or of TAC." (PMID 30761138, 2019).
hair loss (1 paper, 2024). "Conversely, rs4880 (SOD2) was found in 73.43% of patients without hair loss compared to 52.63% of those with hair loss (p = 0.061)." (PMID 39539630, 2024).
hereditary hemochromatosis (1 paper, 2025). An inherited metabolic disorder characterized by iron accumulation in the tissues. "It is also worth noting that independent studies have previously shown that iron overload inactivates SOD2 in yeast, and a similar effect was reported in a mouse model of hereditary hemochromatosis." (PMID 41372147, 2025).
hereditary spastic paraplegia (1 paper, 2016). Hereditary spastic paraplegias (HSP) comprise a genetically and clinically heterogeneous group of neurodegenerative disorders characterized by progressive spasticity and hyperreflexia of the lower limbs. "We have previously observed decreased SOD2 protein levels due to misfolding and degradation of SOD2 protein followed by increased oxidative protein damage (protein carbonylation) in a mouse model for hereditary spastic paraplegia due to HSP60 haplosufficiency." (PMID 27774450, 2016).
Hutchinson-Gilford syndrome (1 paper, 2014). "Hutchinson-Gilford syndrome (HGS) is a progeria displaying excess ROS production, and increased mRNA levels and protein content for mitochondrial Mn superoxide dismutase (SOD-2), along with a drop in the ATP (50%) content of HGS fibroblasts versus controls." (PMID 24876913, 2014).
hypertensive heart disease (1 paper, 2021). Abnormal enlargement of the heart resulting from long-standing hypertension. "The findings of the PPI network indicated that SOD1 and SOD2 were predicted as the potential genes of AS-IV in the treatment of hypertensive heart disease." (PMID 34803698, 2021). "Our findings indicated that the targeted genes of AS-IV against hypertensive heart disease are involved in oxidative stress and inflammation, including SOD2, SOD1, IL-6, TNF, and IL-1β." (PMID 34803698, 2021). "In the present study, we found that AS-IV up-regulated the expression of SOD1 and SOD2, improved the activities of SOD and GSH, and decreased the MDA level, indicating that AS-IV inhibited the progression of hypertensive heart disease via inhibition of oxidative stress." (PMID 34803698, 2021).
hyperthyroidism (1 paper, 2017). Overactivity of the thyroid gland resulting in overproduction of thyroid hormone and increased metabolic rate. "SOD2 expression was also significantly increased in hyperthyroidism rats, but it was significantly decreased in liver and brain tissues by the treatment of MOK pharmacopuncture at 3 mg/kg." (PMID 29246135, 2017).
hypovitaminosis D (1 paper, 2023). "Thus, despite the limitations, different genotypes of BsmI SNP of the VDR gene modulated the expression of the VDR, CYP24A1, and SOD2 genes even though they did not alter the circulating levels of vitamin D in individuals with hypovitaminosis D." (PMID 37630755, 2023).
idiopathic dilated cardiomyopathy (1 paper, 2018). Decreased function of the heart associated with cardiac enlargement and congestive heart failure, of unknown cause. "Despite documented association between mutations in the SOD2 gene and several pathologies, including sporadic motor neuron disease, idiopathic dilated cardiomyopathy (IDC), premature aging (progeria), and cancer, the role of SOD2 in cancer cells, such as in CRC cells, is not fully understood." (PMID 30103475, 2018).
ileitis (1 paper, 2021). "Mito-Tempo is a mitochondrial-targeted superoxide dismutase 2 (SOD2) mimetic shown to have antioxidant properties and to ameliorate ileitis in mice driven by mitochondrial dysfunction." (PMID 34072441, 2021).
inflammatory skin disease (1 paper, 2021). Inflammatory skin disorders covers a broad category that includes many conditions ranging in severity, from mild itching to grave medical health complications These disorders are common in people of all ages and races. "In AZ(−) conditions, THDC up-regulated genes increased as part of the unhealthy skin signature (P < 0.01), which is a set of genes increased in diverse types of inflammatory skin disease (e.g., SOD2, PRMT1, RCC1)." (PMID 34445461, 2021).
insulinoma (1 paper, 2011). "Studies utilizing overexpression of GPX1, SOD1 (Cu/Zn SOD), SOD2 (MnSOD), or SOD mimetic administration in insulinoma cell lines such as NIT-1 and INS-1 afforded protection from ROS and reactive nitrogen species (RNS) in vitro." (PMID 21647409, 2011).